AURKA (aurora kinase A)
Diseases named in the same sentence as AURKA in open-access papers (continued):
Sharing a sentence is not in itself a finding about the gene and the disease.
non-small cell lung carcinoma (17 papers, 2011 to 2026). A group of at least three distinct histological types of lung cancer, including non-small cell squamous cell carcinoma, adenocarcinoma, and large cell carcinoma. "tRF-Leu-CAG is a new diagnostic marker and potential therapeutic target in non-small-cell lung cancer, involved in regulating AURKA." (PMID 33860037, 2021). "Moreover, AURKA is also significantly upregulated and associated with poor prognosis in non-small cell lung cancer (NSCLC)." (PMID 38521813, 2024). "According to recent studies, higher AURKA expression demonstrated poor prediction outcomes for non-small cell lung cancer." (PMID 36984548, 2023). "Quantitative real-time PCR and immunohistochemistry analysis on matched cancer and corresponding normal tissues from surgically resected non-small cell lung cancers (NSCLC) have been performed aiming to explore the expression levels of AURKA gene." (PMID 21718475, 2011). "AURKA inhibition has been shown to increase chemosensitivity in lung and ovarian cancer cell lines and has been suggested as a mechanism to increase radiosensitivity in non-small cell lung cancer, as well as other cancers." (PMID 31647033, 2019). "Notably, AURKA has been implicated in phosphorylating LKB1, resulting in the suppression of the LKB1/AMPK signaling pathway and promoting the proliferation, invasion, and migration of non-small cell lung cancer cells." (PMID 38521813, 2024). "Furthermore, it was demonstrated that up-regulating the expression of miR-32 via administration of tanshinone, could suppress AURKA expression leading to inhibition of Non-Small Cell Lung Cancer (NSCLC)." (PMID 36067794, 2022).
multiple myeloma (15 papers, 2013 to 2026). "AURKA was selected at this point in time when the GEP-R was developed as we had previously shown it to be expressed in approx. 30% of previously untreated myeloma patients and is associated with adverse survival." (PMID 31242924, 2019). "AURKA has been reported to be associated with myeloma resistance and early disease recurrence." (PMID 34260414, 2021). "Upon inhibition of AURKA, it induces G2/M arrest and aneuploidy, which subsequently leads to senescence or apoptosis in multiple myeloma cells in vitro." (PMID 38606093, 2024). "MLN8237, a small molecule AURKA inhibitor, inhibited multiple myeloma proliferation by inducing cell injury and apoptosis." (PMID 39272790, 2024). "In multiple myeloma, miR-137 is downregulated, thus inducing drug resistance and chromosomal instability by targeting AURKA." (PMID 34094916, 2021). "Our previous study demonstrated that as many as 5 of 17 genes found to be significantly up-regulated in ALDH1+ myeloma cells encode cell cycle-dependent protein kinases; specifically, CDC2, TTK, AURKA, AURKB and, of importance here, NEK2." (PMID 25230277, 2014). "AURKA suppression significantly inhibited cellular proliferation in myeloma cells." (PMID 41562677, 2026). "Analysis of public GEO datasets showed that AURKA is overexpressed in patient-derived myeloma samples compared with normal controls, with especially elevated expression in plasma cell leukemia, where higher AURKA levels may be linked to worse outcomes." (PMID 41562677, 2026). "Inhibition of AURKA by ENMD-2076 also promotes cell cycle arrest in the G2/M phase and cell death via apoptosis in multiple myeloma cells in vitro." (PMID 38606093, 2024). "Examples include the discovery of a miR-29b-dependent pathway, the finding that miR-137 induces genomic instability in an aurora kinase A (AURKA)-dependent manner and the observation that regulation of DNA ligase III in myeloma involves miR-22." (PMID 31139207, 2019). "Expression of some genes connected with centrosome formation and function (AURKA, AURKB, CETN2, and PLK4) was significantly different between hyperdiploid and non-hyperdiploid myeloma patients." (PMID 23522059, 2013).
head and neck squamous cell carcinoma (13 papers, 2011 to 2026). A squamous cell carcinoma that arises from any of the following anatomic sites: lip and oral cavity, nasal cavity, paranasal sinuses, pharynx, larynx, and salivary glands. "The combination of alisertib and pembrolizumab showed acceptable tolerability and disease stabilization in immunotherapy-resistant patients, whereas AURKA inhibition decreased resistance in retinoblastoma protein-deficient head and neck squamous cell carcinoma." (PMID 41562677, 2026). "Also, Reiter and his colleagues showed that the up-regulation of AURKA mRNA may play a critical role in the tumor progression of head and neck squamous cell carcinoma and provides useful information as a prognostic factor for patients." (PMID 25428915, 2014). "Besides, WEE1 inhibition effectively reversed resistance to BRAF inhibitors and AURKA inhibitor (MLN8237) in HPV- HNSCC (head and neck squamous cell carcinoma." (PMID 38231277, 2024). "Moreover, NVP-TAE226 inhibits the AURKA/AKT/FAK signaling pathway by inhibiting FAK, thereby waning cell invasion and migration in head-and-neck squamous cell carcinoma." (PMID 35205315, 2022). "Overexpression and hyperactivation of AURKA and AURKB have major roles in tumorigenesis, and therefore their inhibitors are already regarded as promising therapeutics for various types of cancer, including head and neck squamous-cell carcinoma." (PMID 25936657, 2015). "AURKA expression is involved in the epithelial-mesenchimal transition (EMT) of nasopharyngeal carcinoma and its inhibition reduces cell invasion in hepatocellular and in head/neck squamous cell carcinoma." (PMID 21718475, 2011).
osteosarcoma (12 papers, 2012 to 2024). A usually aggressive malignant bone-forming mesenchymal neoplasm, predominantly affecting adolescents and young adults. "U2OS osteosarcoma cells treated with those compounds displayed a decrease in AurkA auto-phosphorylation and mitotic spindle defects consistent with AurkA activity inhibition." (PMID 39195284, 2024). "In this regard, Aurora kinase A (AURKA) inhibition inhibits osteosarcoma cell division by preventing MT stabilization to form the mitotic spindle." (PMID 36046434, 2021). "AURKA and CENPA had, respectively, been identified as a susceptibility gene and an independent poor prognostic factor for osteosarcoma." (PMID 26337976, 2015). "However, the only research applied for Aurora Kinase A and B on osteosarcoma was in vitro, thus further investigation may evolve a new prognostic marker." (PMID 24667142, 2014). "Next, we used three inhibitors (Dinaciclib, Alisertib, or Barasertib), which targeted the top candidate hits (CDK members, AURKA, or AURKB) to validate the screen results in multiple osteosarcoma cell lines." (PMID 37419907, 2023). "For example, AURKA was specifically expressed in proliferating osteoblastic osteosarcoma cells, while CDK4 was widely expressed in all subtypes of osteosarcoma cells." (PMID 37457661, 2023). "We then performed qRT-PCR to assess the expression of five hub genes (TOP2A, CDK1, MAD2L1, AURKA and RRM2) in human normal osteoblast cells and osteosarcoma cells." (PMID 34156352, 2021). "Subsequently, we performed qRT-PCR to measure TOP2A, CDK1, MAD2L1, AURKA and RRM2 expression in human normal osteoblast cells (hFOB 1.19) and osteosarcoma cells (MG63, U208 and 143B)." (PMID 34156352, 2021). "For instance, AURKA, MCM2 and CCNB2 which are among the prototypical genes showing overexpression in the most aggressive osteosarcomas were among the genes that were significantly reduced in OS cells treated with 5-AzadC and 4-PBA." (PMID 22957032, 2012).
prostate adenocarcinoma (12 papers, 2017 to 2025). "Oncogenic drivers, including Aurora kinase A (AURKA) and MYCN, further promote the transition from prostate adenocarcinoma to NEPC by stabilizing neuroendocrine transcriptional regulators and disrupting epithelial lineage commitment." (PMID 40722714, 2025). "Amplification and overexpression of MYCN and AURKA genes have been observed in confirmed t-NEPC tissue, and both induce a neuroendocrine cell phenotype in prostatic adenocarcinoma cells through transcriptional reprogramming mechanisms." (PMID 34386489, 2021). "Using tissue sourced from benign prostate, prostate adenocarcinoma, and NEPC, a significant overexpression and gene amplification of the protooncogenes MYCN and its stabilising cofactor Aurora kinase A (AURKA) were discovered in 40% of NEPC and 5% of prostate adenocarcinomas." (PMID 39682746, 2024). "Four out of 33 (12.1%) cancer types show expression of AURKA with log2 (transcripts per million [TPM] + 1) values < 2, including brain lower-grade glioma (LGG), prostate adenocarcinoma (PRAD), pheochromocytoma and paraganglioma (PCPG) and THCA versus other tumors." (PMID 33451333, 2021).
head and neck cancer (11 papers, 2007 to 2024). A primary or metastatic malignant neoplasm affecting the head and neck. "Alisertib is an investigational Aurora kinase A-specific inhibitor, effective in head and neck cancer cells." (PMID 35994477, 2022). "Overexpression of AURKA induces aneuploidy and chromosomal instability and overrides the mitotic spindle checkpoint, driving progression in head and neck cancer." (PMID 26468983, 2015). "Previous and recent studies showed that E6 encoded by HPV16 binds to AurA, and this may lead to increased Aurora kinase A levels in head-and-neck cancers." (PMID 37173932, 2023). "It will be interesting to further investigate the connection between AurkA protein stabilization and cancer, initially proposed when constitutive stabilizing phosphorylation of Ser51 was shown in head and neck cancer, in light of the contribution to its nuclear-localized oncogenic functions." (PMID 36797043, 2023). "We used this database to assess the dependence of a large panel of head and neck cancer cell lines on the expression of PLK1, AURKA, TPR, NUF2, NDC80, and TTK." (PMID 39392349, 2024). "Additionally, AZD1775 in combination with the Aurora Kinase A inhibitor, alisertib, also demonstrated an enhanced anti-tumor effect with increases in apoptosis and γ-H2AX in head and neck cancers." (PMID 32204315, 2020).
oral cancer (11 papers, 2012 to 2025). "Lee at al. identified an association between a genetic variant (rs2273535) in the AURKA gene and oral cancer." (PMID 29678897, 2018). "A previous study demonstrated that the AURKA 91A (rs2273535) allele polymorphism is associated with a high risk of oral cancer." (PMID 28152093, 2017). "Among the 876 oral cancer patients, only patients with the AURKA rs2064863 gene had a 1.365-fold higher risk of stage III or IV OSCC (95% CI 1.029–1.811) than did patients with the rs2064863 wild-type gene (p = 0.031)." (PMID 28152093, 2017). "Genotyping and allele frequency of AURKA single nucleotide polymorphism in oral cancer and normal controls." (PMID 28152093, 2017). "Associations of the combined effect of AURKA gene polymorphisms and betel nut chewing with the susceptibility to oral cancer among 1420 smokers." (PMID 28152093, 2017). "Early research demonstrated that the AA genotype of AURKA rs2273535 T>A could increase the risk of oral cancer." (PMID 31636670, 2019). "However, the possibility of an association among the advanced stage, AURKA expression level, and AURKA genotype, as well as the effects of the AURKA genotype on oral cancer risk, require further investigation." (PMID 28152093, 2017). "Effect of AURKA rs2064863 polymorphism on clinical statuses in 786 male oral cancer." (PMID 28152093, 2017). "The serine-threonine kinase, AURKA, is one of the important mitosis regulators and is upregulated in many cancers including oral cancer." (PMID 35378133, 2022). "Upregulation of AURKA is reported in many cancers including oral cancer as compared to respective normal tissues." (PMID 35378133, 2022). "Selective inhibitors of AURKA have been developed for the treatment of solid tumors and have been tested in preclinical studies against oral cancer." (PMID 29109723, 2017). "Both aurora kinase A (also named as STK15) and B had been suggested to be correlated with oral cancer." (PMID 22283874, 2012). "Among the 1420 smokers, the AURKA polymorphism carriers with the betel nut chewing habit had a higher risk of oral cancer than AURKA wild-type (WT) carriers without the betel nut chewing habit." (PMID 28152093, 2017).
medulloblastoma (10 papers, 2012 to 2023). A malignant, invasive embryonal neoplasm arising from the cerebellum. "The expression levels of AURKA and KIF20A were discovered to be linked with the prognosis of medulloblastoma patients." (PMID 35574421, 2022). "Aurora kinase A inhibition has been shown to further increase the chemosensitivity of medulloblastoma cells, leading to a potential for reducing the dose of damaging chemotherapy." (PMID 28333115, 2017). "Highlights of the available literature suggest that targeting Aurora kinase A is an effective way of disrupting MYC stability in c-MYC/MYCN-dependent malignancies including medulloblastoma." (PMID 28333115, 2017). "Our previous report on the importance of aurora kinase A in medulloblastoma cell proliferation further validates this new methodology of identifying genes by integrated genomic analysis." (PMID 24661910, 2014). "Analysis of protein kinase gene expression revealed that expression of multiple protein kinases was altered in medulloblastoma, including several components of the mitotic machinery such as aurora kinase A and PLK1." (PMID 22390279, 2012). "Importantly, it has been reported that the primary cilia-mediated oncogenic signals of Hedgehog, Wnt, and Aurora kinase A are involved in the tumorigenesis and tumor progression of basal cell carcinoma and some types of medulloblastoma." (PMID 37006607, 2023). "Thus, PTPRD is likely to have a tumor suppressor function in any type of cancer with MYCN amplification, including other pediatric cancers such as medulloblastoma and rhabdomyosarcoma, or in adult tumors that are dependent on high AURKA levels." (PMID 22305495, 2012). "In conclusion, This study found that aurora kinase A (AURKA) and kinesin family member 20A (KIF20A) may be involved in the initiation and development of medulloblastoma, have a close association with prognosis, and may become a potential therapeutic target and prognostic marker of MED." (PMID 35574421, 2022).
nasopharyngeal carcinoma (10 papers, 2011 to 2025). A carcinoma arising from the nasopharyngeal epithelium. "This study comprehensively explored the clinical function of Aurora kinase A (AURKA) gene in nasopharyngeal carcinoma (NPC) and analyzed its potential as a therapeutic target in cancer." (PMID 36072667, 2022). "Similarly, AURKA levels were evaluated in 92 patients with nasopharyngeal carcinoma (NPC) and 93 healthy individuals." (PMID 38590119, 2024). "AURKA knockdown significantly inhibited bladder, gastric, and nasopharyngeal cancer cell growth." (PMID 39585848, 2024). "Indeed, pharmacological inhibition of PLK1 and AURKA demonstrated superior antitumor activity compared with either single drug treatment in nasopharyngeal carcinoma and was minimally harmful to normal epithelial cells." (PMID 39085197, 2024). "However, AURKA expression was involved in the epithelial-mesenchimal transition (EMT) of nasopharyngeal carcinoma." (PMID 21718475, 2011). "In nasopharyngeal carcinoma, YBX1 promotes the expression of AURKA protein by directly binding to AURKA mRNA, thereby promoting the proliferation and invasiveness of nasopharyngeal carcinoma cells." (PMID 40799245, 2025). "AURKA expression is involved in the epithelial-mesenchimal transition (EMT) and invasion of nasopharyngeal carcinoma." (PMID 21718475, 2011). "Indeed, nasopharyngeal carcinoma and diffuse midline glioma cells have shown increased sensitivity to co-inhibition of PLK1 and AURKA compared to BI-2536 or AURKA inhibitors as a single agent." (PMID 39085197, 2024). "AURKA showed a negative correlation with the infiltration of B cells, CD8+ T cells, and T cell regulatory cells, but a positive correlation with CD4+ T cell Th2 in nasopharyngeal carcinoma." (PMID 39585848, 2024).
lymph node metastasis (9 papers, 2009 to 2024). "Interestingly, the high expression of AURKA was associated with lymph node metastasis and larger tumor size in the enrolled CRC patients." (PMID 35166647, 2022). "The expression of AURKA was associated with a high degree of MTC malignancy, as well as cervical lymph node metastasis and recurrence." (PMID 38903715, 2024). "Chi-square analysis suggested that high AURKA expression was positively correlated with advanced T staging, lymph node metastasis and TNM staging." (PMID 36471438, 2022). "In 129 enrolled patients, lymph node metastasis, large tumor size, low Hb level, and AURKA overexpression were prognostic factors for both recurrent free survival (RFS) and overall survival (OS) in univariate analysis." (PMID 28404933, 2017). "AURKA expression was significantly correlated with lymph node metastasis (P<0.001), large tumor size (P<0.001), low Hb level (P=0.038), and recurrence (P<0.001)." (PMID 28404933, 2017). "Univariate analysis showed that the RFS in all 129 cases was significantly influenced by lymph node metastasis (P<0.001), large tumor size (P<0.001), low Hb level (P=0.011), and AURKA expression level (P<0.001)." (PMID 28404933, 2017). "Univariate analysis showed that the OS of all 129 cases was significantly influenced by lymph node metastasis (P<0.001), large tumor size (P<0.001), low Hb level (P=0.004), and AURKA expression (P<0.001)." (PMID 28404933, 2017). "From another point of view, tumors with lymph node metastasis were more often found to have amplification of the AURKA gene than tumors without metastasis, which suggests this gene may have a role in progression and promotion of tumor spread." (PMID 22363777, 2012).